CCL2 (C-C motif chemokine ligand 2)
Diseases named in the same sentence as CCL2 in open-access papers (continued):
Sharing a sentence is not in itself a finding about the gene and the disease.
tumor (continued). "In hepatocellular carcinoma, tumor cells and TAN work together to activate neutrophils in peripheral blood of patients, secrete chemokine CC motif ligand 2 (CCL2) and chemokine CC motif ligand 17 (CCL17), and then promote tumor growth, proliferation, and macrophage growth." (PMID 35965533, 2022). "In CT26 metastasis, blocking monocyte recruitment with α-CCL2 antibody treatment did not alter GLPM levels on the tumor." (PMID 35906202, 2022). "For instance, one chemokine, i.e., CCL2, might be the prominent driver of CCR2+/CX3CR1+ cell recruitment to the tumor, while the second, i.e., CCL7, is more important for homing to specific niches within tumor." (PMID 36685592, 2022). "TAMs participate in tumor angiogenesis by secreting pro-angiogenic factors, including tumor necrosis factor-alpha (TNF-α), Interleukin-1β(IL-1β), C-C motif chemokine ligand 2 (CCL-2), and matrix metalloproteases (MMPs), which are essential for metastasis and development of late-stage cancers." (PMID 35967399, 2022). "In addition, CCL2 and CCL7 are expressed on GBM and enable CCR2+ cells to play a tumor-recruiting role." (PMID 36466873, 2022). "Interestingly, it has been reported that in BC patients, estrogens induce the production of CCL2 and CCL5 within the tumor beds, leading to the recruitment and polarization of macrophages towards a pro-tumorigenic phenotype." (PMID 35309358, 2022). "When the CCL2/CCR2 interaction was blocked, the metastatic dissemination of tumors in the mouse was significantly inhibited, the survival of the mouse was prolonged and the expression levels of tumor-promoting cytokines were reduced." (PMID 36131942, 2022). "Besides, M2-TAMs-mediated CCL2, CCL3, CCL4, CCL5 or CCL20 release also promotes the recruitment of Treg cells into TME, which further suppresses the anti-tumor functions of T cells and NK cells." (PMID 36419877, 2022). "Furthermore, the tumor cells stimulated macrophages into an M2 phenotype, which in turn increased TAM CCL2 secretion promoting monocytes and macrophage accumulation in the TME creating a malignant positive feedback loop and endocrine resistance." (PMID 35804950, 2022). "Furthermore, TANs secrete CCL2 and CCL17, which correlate with tumor size, microvascular invasion, extent of tumor differentiation, staging, and poor survival time." (PMID 36613878, 2022). "In addition, high levels of CXCL8/IL8, IL6, and MCP-1/CCL2 secretion promoted the migration of tumor cells and macrophage-like cells, exacerbating tumor progression." (PMID 36354566, 2022). "CCL2 had the highest serum level in naïve mice, followed by CCL4 and CCL5, and their concentrations increased from the early to late stage of metastasis, just like in mice with the s.c. tumours." (PMID 36241867, 2022). "Furthermore, several chemokine signaling axes also contribute to tumor vasculature generation such as CXCLs/CXCR2, SDF1/CXCR4, and CCL2/CCR2 axis directly or indirectly." (PMID 36324128, 2022). "Another ligand–receptor pair, CXCL1/CXCL8/CCL2/CCL5‐ACKR1 was predicted to act between iCAFs and E1, which might regulate GC tumour progression." (PMID 35184420, 2022). "Here, we showed how deltarasin functions to abrogate a mutant KRAS-initiated in vivo inflammatory loop of tumor-derived CCL2 and myeloid-secreted IL-1β by downregulating the IL1R1 expression of KRAS-mutant tumor cells and thereby abolishing their receptivity to myeloid IL-1β signals." (PMID 35327394, 2022). "Gastric tumor-derived TEX was internalized by macrophages and induced an M1 pro-inflammatory response in macrophages through the activation of NF-κB, which stimulated inflammatory cytokines including GCSF, IL-6, IL-8, IL-1β, CCL2, and TNF-α and promoted tumor cell proliferation and migration." (PMID 35163380, 2022).
tumor (continued). "Recent research in ESCC revealed that upregulated expression of CCL2 could mediate TAMs accumulation via the CCL2-CCR2 signaling pathway, thereby inhibiting the anti-tumor ability of CTLs in TME and promoting immune evasion of ESCC cells." (PMID 36698392, 2022). "The immune cells that reside in the tumor microenvironment include lymphocytes, macrophages and polymorphonucleocytes, many of which migrate into the tumor via chemoattractants such as CSF-1, IL-3 and VEGF, and chemokines such as CCL-2." (PMID 35267430, 2022). "Moreover, the secretion of CCL2, which is dependent on the activation of the TLR-7 receptor in MCs, promotes the recruitment of plasmacytoid dendritic cells (pDCs) to the tumor niche where they differentiate to tumor-killing effector cells." (PMID 35159157, 2022). "Tumor-derived factors such as colony-stimulating factor 1 (CSF1; also known as M-CSF), granulocyte-macrophage colony-stimulating factor (GM-CSF), CC-chemokine ligand 2 (CCL2), CCL7 (or MCP-3), GDNF, IL-33, CXCL12 (SDF-1) and EGF are responsible for myeloid cell recruitment and promote tumor growth." (PMID 36140392, 2022). "CCL2 is a chemokine that regulates monocyte and macrophage migration, and the CCL2/CCR2 axis has been shown to have multiple pro-tumor effects, ranging from mediating tumor growth and angiogenesis to recruiting and usurping host stromal cells to support tumor progression." (PMID 36045408, 2022). "In the CT26 tumour model, we identified early levels of CXCL1, CCL2 and CCL17 as having important roles in predicting tumour growth as well as similar pairwise correlations with factors directly correlating with tumour growth and one another, suggesting they played similar roles in this context." (PMID 35226704, 2022). "We found that cisplatin-pretreated tumor cells stimulate neutrophils which expressed higher levels of cytotoxic effectors, including TNF-α, GZMB, and ELANE, and pro-inflammatory cytokines, such as CCL2, CCL3, CXCL10, CXCL11, and IL12." (PMID 35784745, 2022). "The C‐C motif chemokine ligand 2 (CCL2)/C‐C motif chemokine receptor 2 (CCR2) signaling pathway is widely believed to play an important role in recruiting TAMs, subsequently contributing to tumor progression." (PMID 36698392, 2022). "In the tumor microenvironment, increased C–C motif chemokine ligand 2 [CCL2, also known as monocyte chemoattractant protein-1 (MCP-1)] and IL-6 induce the recruitment of myeloid-derived suppressor cells (MDSCs), which are known to be immune-suppressive cells that inhibit antitumor immunity." (PMID 36380016, 2022). "It is important to note that CCL2 also regulates the infiltration of TAMs into the TME, which, in turn, also produces CCL2 and amplifies the mobilization of more CCR2+ macrophages to the tumor niche." (PMID 36532078, 2022). "The chemoattractant CCL2 molecule has been involved in several cancers for inducing MDSC/TAM tumor infiltration and targeting this chemokine with anti-CCL2 antibodies and/or inhibitors of its major ligand, CCR2, have improved tumor regression in pre-clinical models of several cancers." (PMID 36613562, 2022). "M1-secreted CCL2, CCL5 or IFN-β may increase neutrophil infiltration to the tumor location and contribute to pro-inflammatory neutrophil-targeted tumor regression." (PMID 36325334, 2022). "MCP-1(CCL2) could therefore play a role in immune-suppression, allowing for greater tumor proliferation in the BCW0 mice compared to the other groups." (PMID 35681702, 2022). "Furthermore, radiotherapy induces a significant increase in the recruitment of CCL2 and Ly6C+CCR2+ monocytes in pancreatic ductal adenocarcinoma (PDAC), thereby accelerating tumor proliferation and angiogenesis." (PMID 35702353, 2022).
tumor (continued). "There has been increasing evidence that monocytes are essential premetastatic promoters and are rapidly recruited from the bone marrow, mainly via the CCL2/CCR2 axis, to premetastatic niches, where they promote tumor colonization by secreting angiogenic factors such as VEGFA." (PMID 36460981, 2022). "Evaluating the influence of chemokines in OC, we could conclude that the overexpression of VEGF and CCL2 and the reduction in CCL5 in MA may provide a facilitating pathway for tumor dissemination in the peritoneal cavity." (PMID 36142615, 2022). "In breast cancer, CCL2 and CCL7 have been reported to promote tumor malignancy." (PMID 36347994, 2022). "The immune cells that reside in the tumor microenvironment include lymphocytes, macrophages, and polymorphonucleocytes, many of which migrate into the tumor through the generation of tumoral chemo-attractants such as CSF-1, IL-3, and VEGF and chemokines such as CCL-2." (PMID 35326557, 2022). "In this study, however, the levels of CCL2 were not higher in serum from tumor-bearing rats compared to controls." (PMID 35551231, 2022). "CCL2 and CCL5 secreted by tumor cells are the two main chemokines." (PMID 35493517, 2022). "CCL2 significantly decreased the proportion of CD45+ CD11b+ F4/80+ CD206- (M1-like) TAMs and increased the CD45+ CD11b+ F4/80+ CD206+ (M2-like) TAMs in mouse tumor tissues." (PMID 35851310, 2022). "Numerous cytokines and chemokines known to enhance stromal activity such as TGFB1, TGFB2, TGFB3, CXCL12, CCL2 and IL-6 were found downregulated in 211F MEF cells, suggesting a potential tumor-promoting function of Y211 phosphorylation through regulation of the secretome in the stromal environment." (PMID 35628489, 2022). "TAF modifies the composition of the TME and the development of cancer, and both TAF secreted cytokines (such as CCl2, CXCL1, and IL-6) and ECM could drive the stemness of tumor cells." (PMID 35322024, 2022). "Likewise, CAFs are involved in monocyte recruitment, macrophage differentiation, and polarization toward tumor-promoting, or an M2 phenotype, through the secretion of macrophage colony-stimulating factor 1 (M-CSF1), IL-6, CCL2, and IL-8." (PMID 36010899, 2022). "Considering the crucial roles of CCL2 on TAMs and the crosstalk between TAMs and GC cells in TME, we examined whether tumor cell-derived CCL2 promoted tumor growth in HER2-positive GC tissues by a paracrine TAM-dependent manner." (PMID 35851310, 2022). "We assessed BM cell migration in the presence or absence of a CCL2 production inhibitor, bindarit, in tumor/stroma cocultures (HSC-2 + HDF, HSC-2 + PDS1, and HSC-2 + PDS2)." (PMID 34874922, 2022). "Emodin can inhibit the recruitment of inflammatory cells in the tumor microenvironment, such as CD11b+ and F4/80+, reduce cytokines, such as TNFα, IL1α/β, IL6, CCL2, and CXCL5, and inhibit COX-2 and NOS2 to inhibit the active adhesion, migration and invasion of CRC cells." (PMID 35637953, 2022). "The homeoprotein Six1, a member of the Six family of homeodomain transcription factors, increases the expression of CCL2, CCL5, and vascular endothelial growth factor (VEGF), attracts macrophage infiltration into the tumor, and further leads to CRC tumor growth, progression, and metastasis." (PMID 35935996, 2022). "We further observed other pro-inflammatory cytokines and chemokines [IFN-G, IP10 (also known as CXCL10), MCP-1 (also known as CCL2) and MIP2 (also known as CXCL2)] to significantly elevate, however, only in NR and 129R, the strains that showed the highest tumor growth." (PMID 36037073, 2022). "EZH2 could also restrain the anti-tumor effect of macrophages and NK cells by suppressing the chemotaxis ability of tumors by reducing the expression level of CXCL10, CCL2, and other chemokines." (PMID 36552722, 2022).
tumor (continued). "Second, analyses performed on tumor lysates revealed that chemokines involved in myeloid cell migration (CCL5, CCL2, CCL4), together with inflammatory (IL-1β and TNFα) and pro-angiogenic factors (VEGF-A, VEGFR2, PDGF, Endoglin) were increased in tumors of mice fed a HFHCD." (PMID 36104342, 2022). "Here, early production of CCL2 and CXCL1 may help with shaping the initial myeloid cell compartment in cancer-bearing individuals, which promotes tumour development and production of CCL17 and CXCL10 which in turn modulates recruitment of leukocytes." (PMID 35226704, 2022). "TAM recruitment is mainly mediated by tumor cells and surrounding stromal cells through the release of diverse chemokines, including CCL5 and CCL2, and stromal glycoproteins can promote tumor progression by facilitating TAM recruitment from the circulation and/or local tissue to the tumor site." (PMID 35327584, 2022). "Also, an increase in the plasma level of CCL2 was noticed, and a similar tendency was observed in HCT116 tumour tissue." (PMID 35701366, 2022). "In addition, numerous mediators from EMT-induced tumors produce monocytes (CCL2) and neutrophil chemoattractants (GM-CSF, CXCL8, and GRO); the production of these mediators following the induction of EMT regulate the tumor niche immune landscape." (PMID 36091114, 2022). "One example is an anti-CCL2 (or anti-MCP1) antibody that is able to extend modestly, albeit significantly, the survival of GBM tumor-bearing mice in which a diminution in the number of TAMs in the tumor microenvironment has been observed." (PMID 35214076, 2022). "Simvastatin could decrease CCL3 expression from cancer cells and ICAM-1, VCAM1, IL-6, and CCL2 expression from CaMSCs, disrupting the crosstalk of the cancer cells and tumor microenvironments (TME) and inhibiting tumor progression." (PMID 36430409, 2022). "High-expression PIPKIγ stimulates the AKT-mTOR signaling activation, leading to increased STAT3 phosphorylation and ultimately promoting CCL2 expression which further facilitates macrophage infiltration and suppresses the activation of CRC tumor immune response." (PMID 35935996, 2022). "Expression levels of Ccl2 and Ccl5 were not significantly altered between tumours and corresponding liver tissues from Ccne1f/f and Ccne1−/− animals." (PMID 34830835, 2021). "While many of these estrogen-induced changes can be interpreted as “pro-tumor”, some activities, such as reduction of TGFβ and CCL2-induced recruitment of NK cells, would not." (PMID 34359625, 2021). "Of note, many cytokines which activate the tumour microenvironment, including platelet-derived growth factor, B polypeptide (PDGFB), interleukin-6 (IL6), chemokine (C–C motif) ligand 2 (CCL2), and leukaemia inhibitory factor (LIF) were included as targets of TGF-β." (PMID 33674758, 2021). "Similarly, radiotherapy increased the release of chemokines CCL2 and CCL5 in experimental tumor models." (PMID 34804061, 2021). "Indeed, these studies suggest that the major monocyte recruiting pathways (M-CSF/CSF-1R, CCL2/CCR2, CCL3/CCR1, CCL3/CCR5, CCL5/CCR5 and CX3CL1/CX3CR1) enable tumor survival by supplying the TME with pro-tumorigenic TAMs." (PMID 34988021, 2021). "SPARC deletion promoted ROS generation and increased the production of pro-inflammatory and pro-angiogenic cytokines IL-6, CCL2, VEGF, and TNF-α as well as cytokines with pro-migratory ability, CCL3, CXCL2, CSF-1, and M-CSF, accompanied by greater tumor infiltration by mac1-positive TAMs." (PMID 34209679, 2021). "In addition, overexpression of SPON2 enhanced, while knockdown of SPON2 reduced IL10, CCL2 and CSF1 expression levels and secretion in CRC tumor cells." (PMID 34583750, 2021). "We also developed the novel mice model for specific over-expressing CCL2 in the lung, and verified that the BC organotropic metastasis was not because of the enhanced tumor cell proliferation, but the regulatory expression of CCL2 in the target organ." (PMID 34249913, 2021).
tumor (continued). "Moreover, anti-ILT4 or anti-PD-L1 treatment markedly decreased the expression and secretion of CCL2 and CCL5 in both tumor cell lines with a synergistic effect in the combination treatment group." (PMID 33537094, 2021). "CCR2 expression by tumor cells can respond in a paracrine fashion to CCL2 produced by various non-tumor cells, tumor cells can also produce CCL2 which acts on CCR2 on tumor cells via an autocrine fashion." (PMID 34804061, 2021). "Moreover, evidence surfaced demonstrating that CCL2 and CCL17 expression in TANs was correlated with tumor progression and prognosis in patients with HCC." (PMID 34200529, 2021). "Histopathological analysis of cytokeratin-stained tumor sections revealed that the invasiveness of A3250 tumors was not decreased upon CCL2 KD, suggesting that CCL2 KD primarily decreased metastatic colonization rather than dissemination." (PMID 34824220, 2021). "Moreover, suppressive chemokines such as C-C motif chemokine 2 (CCL2) or CCL5 released from irradiated cells can recruit MDSCs and regulatory CD4 T cells (Tregs) to the tumor site." (PMID 33928081, 2021). "CCL2, CCL3, TIMP-1, and IL-13 are products readily found in an immune response that is driven by M2 macrophages, which correspond to a tumour growth-promoting phenotype that aids tumour cell proliferation, reduction of an antigen-specific immune responses, and increased angiogenesis." (PMID 33494138, 2021). "CAF with tumor-promoting functions secrete growth factors (HGF, IGF1, CTGF, PDGF, VEGF, LIF), cytokines (IL-1, IL-4, IL-6, IL-8, IL-10, TGF-β), and chemokines (CCL2, CCL5, CXCL5, CXCL9, CXCL10, CXCL12), WNT5α, and bone morphogenic protein 4 (BMP4), which promote tumor progression." (PMID 35008832, 2021). "In this study, we demonstrated that CCL2 secreted by tumor cells promotes the migration of 7×2b CAR-T cells, which contributes to 7×2b CAR-T cell recruitment to the tumor site in vivo to fight the tumor." (PMID 34778046, 2021). "These therapies or tumor-specific delivery of GM-CSF, CXCL10, and CCL2 could be successful with chemotherapy or in combination with checkpoint inhibitors." (PMID 34045467, 2021). "We found that while overall tumour growth was not significantly impacted by the absence of properdin, there was significantly less CCL2 chemokine and fewer Gr1+ CD11b+ MDSCs as well as M2 type macrophages compared with wildtype counterparts." (PMID 33494138, 2021). "CCL2 was secreted primarily by the IMR-32-CCL2 xenografts, and the levels were essentially the same in all three mouse groups on day 7 with subsequent changes appearing to correlate with the degree of tumor subduction." (PMID 34778046, 2021). "Administration of HT29-pcDNA-EVs did not have statistical impact on neither tumour growth nor plasma MCP-1/CCL2 levels within the groups of mice injected with either HT29-pcDNA cells or HT29-Snail cells." (PMID 33419021, 2021). "Myeloid-derived suppressor cells are recruited through CCL2 and possibly CXCL1 and CXCL2 (which recruit neutrophils) to the tumor, where their suppressive activity is enhanced by direct contact with mast cells or alternatively matured to less suppressive differentiated cells through histamine." (PMID 34063789, 2021). "Finally, we discuss the effects of cycling hypoxia on the tumor microenvironment, in particular on the expression of VEGF-A, CCL2/MCP-1, CXCL1/GRO-α, CXCL8/IL-8, and COX-2 together with PGE2." (PMID 34639040, 2021). "In order to better match the chemokine secreted by tumor cells, some studies have introduced chemokine receptors such as CCR2b into CAR-T cells through genetic modification and promoted the transport by the large amount of CCL2 secreted by tumor cells." (PMID 34778046, 2021). "The CCL2/CCR2 pathway is strongly associated with MDSC migration into tumors, and a lack of these cytokines can impair the tumor-promoting effects of MDSCs120." (PMID 34403220, 2021).